TDO2 (tryptophan 2,3-dioxygenase)
Description:
Heme-dependent dioxygenase that catalyzes the oxidative cleavage of the L-tryptophan (L-Trp) pyrrole ring and converts L-tryptophan to N-formyl-L-kynurenine. Catalyzes the oxidative cleavage of the indole moiety.
Synonyms: TDO; TO; TRPO; TPH2; HYPTRP
Tractability: Small molecule: a structure with a bound ligand is known; a high-quality ligand is known; it belongs to a druggable protein family. Antibody: the Human Protein Atlas places it where antibodies can reach. PROTAC: its protein half-life has been measured; a small molecule that binds it is known.
Target class: Enzyme; Oxidoreductase
Gene: Protein-coding gene on chromosome 4 (155,854,738 to 155,920,414, forward strand). Ensembl gene ENSG00000151790.
Subcellular location (Human Protein Atlas): Cytosol; Plasma membrane; Basal body; Primary cilium
Pathways (Reactome):
Metabolism: Tryptophan catabolism
Gene Ontology:
Molecular function: heme binding; identical protein binding; L-tryptophan 2,3-dioxygenase activity; protein binding; amino acid binding; metal ion binding
Biological process: L-tryptophan catabolic process; protein homotetramerization; response to cortisol; response to dexamethasone; response to ethanol; response to nitroglycerin
Cellular component: cytosol
Genetic constraint (gnomAD): Loss-of-function variants: 39 observed, 46.15 expected, observed/expected ratio (o/e) 0.85, 90% interval 0.65 to 1.1. The upper end of that interval is the gene's LOEUF score, 1.1, which puts it in group 4 of 6, group 1 being the genes least tolerant of losing a copy. Missense variants: 442 observed, 436.48 expected, observed/expected ratio (o/e) 1.01, 90% interval 0.94 to 1.1. Synonymous variants: 169 observed, 153.21 expected, observed/expected ratio (o/e) 1.1, 90% interval 0.97 to 1.25.
Gene-disease validity (ClinGen):
ClinGen rates the evidence that TDO2 causes each of these diseases.
familial hypertryptophanemia (autosomal recessive): Limited. Familial hypertryptophanemia is characterized by intellectual deficit associated with behavioral problems: periodic mood swings, exaggerated affective responses and abnormal sexual behavior.
Homologues: Orthologues: chimpanzee TDO2 (99% identical), macaque TDO2 (99% identical), dog TDO2 (94% identical), rabbit TDO2 (92% identical), guinea pig TDO2 (89% identical), mouse Tdo2 (89% identical), rat Tdo2 (89% identical), pig TDO2 (83% identical), tropical clawed frog tdo2 (83% identical), zebrafish tdo2a (75% identical), zebrafish tdo2b (75% identical), Drosophila melanogaster v (53% identical), and 1 more.
Diseases named in the same sentence as TDO2 in open-access papers:
TDO2 is named in the same sentence as 117 diseases in open-access papers, as found by Europe PMC text mining. Sharing a sentence is not in itself a finding about the gene and the disease. The quoted sentences say what the papers report.
glioma (33 papers, 2014 to 2025). A benign or malignant brain and spinal cord tumor that arises from glial cells (astrocytes, oligodendrocytes, ependymal cells). "Like IDO-1, high expression of TDO-2 was also associated with worse prognosis, such as in low-grade glioma, clear cell renal cancer, papillary renal cancer, acute myeloid leukemia, mesothelioma, and testicular germ cell tumor." (PMID 34367262, 2021). "In glioma, TDO2 is upregulated and plays a decisive role in tryptophan metabolism, and its expression is related to glioma cell motility." (PMID 40103267, 2025). "Key enzymes such as indoleamine 2,3-dioxygenase (IDO1) and tryptophan 2,3-dioxygenase (TDO2) are commonly overexpressed in human glioma cells, resulting in elevated production of kynurenine." (PMID 40843669, 2025). "Recent studies have demonstrated that IL4I1 activates AhR more potently than IDO1 and TDO2, generating indole metabolites and quinolinic acid that promote tumor progression in gliomas and leukemia by enhancing cancer cell motility and suppression immunity." (PMID 40559961, 2025). "For instance, in data derived from the Rembrandt database, patients with gliomas (WHO grades II–IV) exhibiting high expression of TDO2 and AhR had considerably lower survival rates compared to those with intermediate or low expression." (PMID 38951170, 2024). "The IC50 of the TDO2 enzyme inhibition in murine glioma cells (GL261) transfected with human-TDO2 (GL261-hTDO2) was 0.25 μM." (PMID 37226257, 2023). "During the past decade, TDO2 was found to be overexpressed in various tumors, such as glioma, breast cancer, basal cell carcinoma, melanoma, cervical cancer, and colorectal cancer." (PMID 34423034, 2021). "NTRC 3531‐0 also inhibited mouse TDO (mTDO) in a biochemical assay and in a cellular assay based on a mouse glioma GL‐261 cell line stably overexpressing the full‐length mouse TDO2 cDNA (GL‐261‐mTDO)." (PMID 33471408, 2021). "Expression of tryptophan 2,3-dioxygenase (TDO) is a determinant of malignancy in gliomas through kynurenine (KYN) signaling." (PMID 33870196, 2021). "In contrast to IDO1, whose regulation has been thoroughly characterized and involves tumor suppressor genes, oncogenes, growth factor/cytokine signaling pathways, and epigenetic mechanisms, the regulation of TDO2 in gliomas is not well understood." (PMID 32477324, 2020). "TDO2 is overexpressed in human glioma cells, and this phenomenon correlates with the production of kynurenine and with the expression of AhR target genes, thus indicating the production of a sufficiently large amount of kynurenine for AhR activation." (PMID 32325928, 2020). "To narrow down this list to transcription factors driving TDO2 expression in gliomas, we interrogated TCGA dataset to find transcription factors showing strong transcriptional correlations with TDO2." (PMID 32477324, 2020). "These were glioma A172 only with TDO2 expression, ovarian SKOV3, which only expresses IDO1 and finally the breast cancer cell line BT549, which expresses both enzyme." (PMID 31795096, 2019). "Human glioma cells have been demonstrated to release high levels of kynurenine by constitutively degrading tryptophan through the tryptophan-2,3-dioxygenase (TDO) pathway." (PMID 30501068, 2018). "Recently, TDO2 was shown to be overexpressed in a large panel of tumors, with a specific, and crucial role in glioma progression." (PMID 25881064, 2015). "TDO2 overexpression in high-grade gliomas correlated, with a poor prognosis, implying tryptophan-derived l-kynurenine as an tumor-derived metabolite promoting AhR-driven immune suppression." (PMID 25881064, 2015). "We also showed that TDO-2 was constitutively expressed by the vast majority (approximately 89%) of glioma samples analysed." (PMID 25415278, 2014). "In gliomas, constitutive activation of tryptophan 2,3-dioxygenase (TDO-2) leads to high levels of kynurenine production." (PMID 25324842, 2014).
glioma (continued). "IDO1 and TDO2 are highly expressed in glioma cells proportionally to glioma grade." (PMID 36900311, 2023). "Meanwhile indoleamine 2,3-dioxygenase (IDO)-1/2 and tryptophan 2,3-dioxygenase (TDO)-2 were highly expressed in glioma cells and were proportional to tumor grade, which catalyzed the decomposition of Trp into kynurenine (Kyn), a ligand of the aryl hydrocarbon receptor (AHR)." (PMID 34211978, 2021). "Recently, TDO2 has been verified to strongly expressed in various cancers, including glioma, breast cancer, lung cancer, esophageal squamous cell carcinoma (ESCC), and could affect cancer biological features, including proliferation and metastasis, directly." (PMID 33542896, 2020). "The enzymatic degradation of tryptophan (Trp) to kynurenine (Kyn), mediated by indoleamine-2,3-dioxygenase-1 (IDO1) or tryptophan-2,3-dioxygenase (TDO2), is a key immunosuppressive pathway operative in gliomas and other types of tumors, and an emerging drug target in cancer immunotherapy." (PMID 32477324, 2020). "Moreover, evidence has emerged to suggest that upregulated IDO1 and TDO2 expression within the tumor was correlated with decreased OS of patients with glioma." (PMID 28389631, 2017). "TDO-2-dependent production of KYN by gliomas might be a novel mechanism for suppressing anti-tumor immunity and supporting tumor growth through activation of the AhR." (PMID 25415278, 2014). "TDO-2 was constitutively expressed by the vast majority (approximately 89%) of gliomas analysed." (PMID 25415278, 2014). "TDO-2 was expressed by all of glioma analysed when stimulated with IFN-γ." (PMID 25415278, 2014). "In contrast to previous approaches, here, we used an unbiased search for regulators of constitutive TDO2 expression in a GBM cell line using iteratively deleted TDO2 reporter constructs to show that C/EBPβ plays an important role in driving TDO2 expression in glioma cells." (PMID 32477324, 2020). "Nonetheless, the use of small-molecule compounds to modulate IDO1/2, TDO2, and AhR in glioma and meningioma cell lines has already proven that in contrast to enzyme inhibition, AhR antagonists markedly reduce tumor cell viability, i.e., AhR may be a therapeutic target in these types of cancer." (PMID 32325928, 2020). "There is no data on the effects of lipid peroxidation products on expression and TDO in OS, but in human glioma cell lines, PGE2 can upregulate TDO2." (PMID 38674143, 2024). "WB results of intracranial glioma tissues further show that, compared to Control group, the expression of PD-L1, CCL2 and TDO2 was increased in CYB561D2 infected gliomas while co-infection with DN-STAT3 fully rescued this effect." (PMID 34372858, 2021). "To investigate whether CYB561D2-activated STAT3 induces the expression of immunosuppressive genes in gliomas, we measured protein expression of FASLG, TGF-β2, CD70, PD-L1, PD-L2, CCL2 and TDO2 in U251 and U87 transfected with CYB561D2 plasmid for 48 h." (PMID 34372858, 2021).
breast cancer (20 papers, 2019 to 2026). A primary or metastatic malignant neoplasm involving the breast. "The expression of TDO2 and IDO1 is upregulated in breast cancer, with high levels of TDO2 closely linked to poor patient prognosis." (PMID 39973065, 2025). "In this study, using TCGA data, HSD17B7, ACADL, ME1, MAOA, and TDO2 were identified as the top five DEGs related to FA metabolism in breast cancer tissues." (PMID 36936412, 2023). "TDO2 overexpression has been described in many cancers including glioblastoma, breast cancer, and lung cancer." (PMID 34101386, 2021). "Overexpression of TDO2 in triple negative breast cancer facilitated anoikis resistance and enhanced the metastatic capability of breast cancer cells in vivo." (PMID 33542896, 2020). "Publicly available data confirmed that higher expression of TDO2 RNA in breast cancers correlated with worse OS and decreased distant metastasis-free survival, which is inconsistent with our data on primary uveal melanoma with TDO2 RNA expression." (PMID 32050636, 2020). "TDO2 is constitutively expressed in various cancer cells, such as hepatocarcinoma, bladder carcinoma, breast carcinoma, colorectal carcinoma, lung carcinoma, and glioblastoma, playing a role in immune surveillance and tumor biology." (PMID 33542896, 2020). "Although primary breast cancer tumors were examined in these clinical datasets for expression levels of TDO2, AhR, and ZEB1, these genes may be expressed at even higher levels in circulating tumor cells (anchorage-independent condition)." (PMID 39311710, 2024). "It has been reported that TDO2 expression is higher in PR-negative versus PR-positive breast cancer tissues, suggesting that progesterone may inhibit TDO2 expression via PR in breast cancer cells." (PMID 35064560, 2022). "Furthermore, studies on targeting tryptophan catabolism enzymes, such as indoleamine-2,3-dioxygenase (IDO1/IDO2), and tryptophan-2,3-dioxygenase (TDO/TDO2), which are expressed by many immune cells and solid tumors, including breast cancer are underway." (PMID 33747948, 2021). "This section will focus on three enzymes, CD73, HO-1 and TDO2, that were identified by manipulating breast cancer EMT by our group and the Weinberg group and summarize how each may impact breast cancer metastasis and anti-tumor immunity." (PMID 34832904, 2021). "Targeting the TDO2-kynurenine axis may represent a promising strategy to restore TLS formation and enhance immunotherapy responsiveness in breast cancer." (PMID 41799509, 2026). "Furthermore, the average of the expression of TDO2, AhR, and ZEB1 genes is higher in basal-like breast cancer (TNBC) than that in luminal A/B [estrogen receptor–positive (ER+)] breast cancer and when generally comparing ER− versus ER+ tumors." (PMID 39311710, 2024). "The remainder of this review will focus on the factors identified by EMT manipulation (CD73, HO-1, TDO2, GM-CSF, M-CSF, CHI3L1 and OPN) and will highlight preclinical and clinical studies that demonstrate how each impact breast cancer metastasis and immune suppression." (PMID 34832904, 2021). "TDO2, for instance is expressed in diverse tumor entities including breast cancer, bladder cancer, hepatocellular carcinoma, melanoma, non-small cell lung cancer, ovarian carcinoma, renal cell carcinoma, and GBM, where it promotes tumor cell motility and suppresses T cell proliferation and function." (PMID 31866995, 2019). "In addition, studies show upregulation of TDO2 expression seen in estrogen-receptor-negative but not in estrogen-receptor-positive breast cancer, suggesting that expression of TDO2 may be under negative regulatory control by estrogen in this setting." (PMID 35327363, 2022).
glioblastoma (17 papers, 2018 to 2026). The most malignant astrocytic tumor (WHO grade IV). "TDO2 demonstrates constitutive overexpression in high-grade gliomas, particularly glioblastoma(GBM), serving as an independent biomarker for tumor aggressiveness and poor prognosis." (PMID 41602107, 2026). "The present study aimed to investigate the expression of IDO1/2, TDO2, and AhR in glioblastoma tissues of newly diagnosed patients." (PMID 38951170, 2024). "The analysis of comcomitant IDO1/2, TDO2, AhR expression in glioblastoma and its relationship with the tumour environment potentially will help to elucidate this interplay." (PMID 38951170, 2024). "IDO1 and TDO2 expression have previously been shown in glioblastoma cell lines 24-29, and in glioblastoma tissue 26, 27, 30-33." (PMID 34646367, 2021). "We previously found that HIF1α downregulates the expression of the Trp-catabolizing enzyme tryptophan-2,3-dioxygenase (TDO2) in human glioblastoma cells." (PMID 33679737, 2021). "Alternative routes of tryptophan catabolism via tryptophan-2,3-dioxygenase (TDO) may be of special interest in glioblastoma, as this gene is highly expressed in glioblastoma." (PMID 32235752, 2020). "The pathways regulating TDO2 in tumors are poorly understood; using unbiased promoter and gene expression analyses, we identify a distinct CCAAT/enhancer-binding protein β (C/EBPβ) binding site in the promoter of TDO2 essential for driving constitutive TDO2 expression in glioblastoma cells." (PMID 32477324, 2020). "Notably, the 52-kDa FK506-binding protein (FKBP52) is involved in mechanisms that suppress tryptophan-2,3-dioxygenase (TDO)-mediated tryptophan catabolism in glioblastoma." (PMID 30314361, 2018). "In addition, HIF1α is involved in the regulation of miR-210-3p, CXCR7, CXCR4, IDH1, C-Met, SF/HGF, the S100A4/NMIIA axis, NO, VEGF, BAG3, and TDO2, and influences various aspects of the glioblastoma biology such as angiogenesis, invasion, metabolism, and therapy resistance." (PMID 38893207, 2024). "Our work shows that glioblastoma patients with high expression of IDO1/2, TDO2 and AhR at diagnosis have a poorer prognosis compared to patients with low expression levels." (PMID 38951170, 2024). "Our study aimed to examine the expression of the key KP proteins TDO2, IDO1/2 and AhR, in newly diagnosed glioblastoma patients and their correlation with survival." (PMID 38951170, 2024). "Immunohistochemical analysis on glioblastoma TMA cores showed variable cytoplasmic expression of IDO1, IDO2, and TDO2, while AhR showed variable nuclear expression in tumour cells across GBM patients." (PMID 38951170, 2024). "further suggests that IL4i1 activates the expression of AHR, IDO, and TDO2, which collectively suppress tumor immunity in the hypoxic TME of glioblastoma derived GBM cells, thereby promoting cancer progression." (PMID 38605962, 2024). "The expression of select AHR target genes, including AHR itself, positively correlated with TDO2 expression and to a lesser extent with IDO1 expression, pointing towards TCE-mediated AHR activation in glioblastoma." (PMID 34646367, 2021). "These latter authors also reported TDO2 expression in intratumoral pericytes of most cancers and confirmed the absence of co-expression of IDO1 and TDO2 in glioblastoma that can be deduced from other data." (PMID 36286592, 2022). "Furthermore, the functional ortholog of IDO, TDO2 (tryptophan-2,3-dioxygenase), was found to be significantly downregulated in a HIF-1α dependent manner in glioblastoma cells exposed to hypoxia." (PMID 35211123, 2022).